STAT3 (signal transducer and activator of transcription 3)
Diseases named in the same sentence as STAT3 in open-access papers (continued):
Sharing a sentence is not in itself a finding about the gene and the disease.
hepatocellular carcinoma (continued). "Cell surface GRP78 was reported to facilitate cell proliferation and migration by activating PI3K and MAPK pathways in hepatoma cells, blocking TGF-β signaling in HeLa cells, and inducing STAT3 signaling in hepatocellular carcinoma cells." (PMID 38378560, 2024). "Oleocanthal inhibits the phosphorylation and nuclear translocation of STAT3 in melanoma and hepatocellular carcinoma." (PMID 39203892, 2024). "In hepatocellular carcinoma cells, melatonin therapy reverses the downregulation of macrophage PD-L1 expression through the inhibition of the STAT3-mediated signaling pathway.." (PMID 38195554, 2024). "What’s more, GOLM1 also acts as a positive regulator of Programmed Cell Death Ligand 1 (PD-L1) expression via the EGFR/Signal Transducer and Activator Of Transcription 3 (STAT3) signaling pathway in the human hepatocellular carcinoma." (PMID 39190284, 2024). "Celastrol suppressed both constitutive and stimulated STAT3 activation in hepatocellular carcinoma, and this inhibition was mediated by inhibiting the expression of upstream kinase c-Src and Janus-activated kinase-1 and -2." (PMID 38397437, 2024). "Domperidone induced triple-negative breast cancer cell apoptosis via JAK/STAT3 Signaling, and domperidone prevented males from hepatocellular carcinoma in a preclinical trial." (PMID 38528618, 2024). "In AEG-1-C75S liver, activation of cell proliferation and invasion were detected which were associated with activation of oncogenic MAP2K4, MAP3K1, TGFA, NRF2, and STAT3 signaling ultimately contributing to hepatocellular carcinoma." (PMID 38677511, 2024). "By investigating the impact of vitexin on the STAT3 signaling pathway and key cancer markers, researchers have demonstrated that vitexin can successfully disrupt the sustained activation of JAK1, JAK2, and STAT3 in hepatocellular carcinoma (HCC) cells." (PMID 38915462, 2024). "There is also evidence in hepatocellular carcinoma that increased STAT3 phosphorylation stimulates the expression of DRP1." (PMID 39262325, 2024). "Another study showed that metformin induced ferroptosis and increased sorafenib sensitivity via regulation of ATF4 (activating transcription factor 4) and STAT3 (signal transducer and activator of transcription 3) in hepatocellular carcinoma cells." (PMID 39247188, 2024). "One example is TTI-101, a novel orally delivered small molecule inhibitor of STAT3 utilized in clinical trials initiated to address STAT3-driven disease in hepatocellular carcinoma (NCT05440708) and metastatic breast cancer (NCT05384119)." (PMID 38339245, 2024). "Sorafenib combined with the triterpenoid cucurbitacin from Cucurbitaceae enhanced apoptosis in HepG2 and Huh7 human hepatocellular carcinoma cells by inhibiting STAT3 activity." (PMID 38527038, 2024). "Cytokine-signaling-related proteins associated with lipid rafts include, for example, IL-2 and IL-15 receptor subunits in T cells, interferon receptors and STAT1 in macrophages, STAT1 and STAT3 in hepatoma cells." (PMID 39563446, 2024). "For example, the IL-6/STAT3 pathway has been identified as a promoter of angiogenesis in hepatocellular carcinoma by enhancing endothelial cell migration and angiogenesis." (PMID 39695099, 2024). "Clinical correlation analysis showed that the mRNA levels of STAT3 were positively correlated with DTX4 in paracancerous tissue of human clinical hepatocellular carcinoma samples." (PMID 39346550, 2024). "Extensive research highlights the pivotal role of signal transducer and activator of transcription 3 (STAT3) in promoting hepatocellular carcinoma (HCC) progression." (PMID 39664573, 2024). "Hepatoma cells showed elevation of p-Gab1, along with an increase in STAT3 and ERK activation, upon treatment with HGF (ligand of HGF receptor/c-Met) and CCL4." (PMID 38935609, 2024).
hepatocellular carcinoma (continued). "Coexpression of OCT4 and NANOG stimulates CSC properties and invasiveness through Stat3/ Snail signaling in hepatocellular carcinoma, while the knockdown of OCT4 decreases invasiveness in pancreatic and gastric cancer cells." (PMID 37529165, 2023). "Similar studies reported the down-regulation of PD-L1 via chrysin through the STAT3 (Signal transducer and activator of transcription factor 3) and NF-κB (Nuclear factor kappa B) pathways in hepatocellular carcinoma." (PMID 37067635, 2023). "In the present study, we found that metformin promoted ferroptosis and sorafenib sensitivity in hepatocellular carcinoma cells via ATF4/STAT3." (PMID 37326750, 2023). "Secondly, more comprehensive in vivo and in vitro studies are necessary to elucidate the mechanisms of TUG1 promotes hepatocellular carcinoma immune evasion via upregulating the JAK2/STAT3/PD-L1 signaling pathway." (PMID 37813900, 2023). "Further in vivo studies of an HCCLM3 hepatocellular carcinoma mouse model showed that the level of circulating VEGF decreased after STAT3 ASO treatment." (PMID 38067351, 2023). "Exons 1 and 4 of SOD2 transcripts were back-spliced to develop circSOD2, inducing epigenetic alteration and driving hepatocellular carcinoma progression by activating the JAK2/STAT3 signaling pathway." (PMID 38139387, 2023). "Research confirmed that there was a high expression of STAT3 in hepatocellular carcinoma, which was closely related to metastasis and tumor grades." (PMID 37333486, 2023). "Based on the previous findings, it is presumed that the high expression of HIF-1α in hepatocellular carcinoma tissues is positively correlated with STAT3 and VEGF." (PMID 37333486, 2023). "In hepatocellular carcinoma cells, niclosamide inhibits cell viability, clone formation, and induces apoptosis by deactivating STAT3 phosphorylation and downregulating antiapoptotic proteins, Mcl-1, and survivin." (PMID 37627178, 2023). "Metformin has been shown to induce iron apoptosis and increase ROS levels in hepatocellular carcinoma cells via ATF4/STAT3, thereby decreasing hepatocellular carcinoma cell resistance to sorafenib." (PMID 38274225, 2023). "As with colorectal cancer, chemical RhoA inhibitor attenuated STAT3 activation in hepatoma cell line." (PMID 37752569, 2023). "On the basis of the previous findings, we deduced that the high expression of HIF-1α in hepatocellular carcinoma cells is positively correlated with STAT3 and VEGF." (PMID 37333486, 2023). "Here we found that CDK5 and HIF1α can positively regulate DHHC7 expression and there is a positive feedback loop formed by DHHC7, STAT3, and HIF1α, which contributes to the malignancy of hepatic carcinoma." (PMID 38051779, 2023). "This study was designed to investigate the promotion of ferroptosis and sorafenib sensitivity by metformin in hepatocellular carcinoma cells via ATF4/STAT3." (PMID 37326750, 2023). "In another study of hepatocellular carcinoma, IL-37 converted M2 TAMs into M1 cells by inhibiting the IL-6/STAT3 signaling pathway." (PMID 38033495, 2023). "lncRNA DILC can inhibit multiple signaling pathways such as NF-κB and STAT3 to affect the proliferation of hepatocellular carcinoma stem cells by suppressing the transcription of IL-6." (PMID 37480035, 2023). "At present, few studies confirmed the effect of curcumin on the HIF-1α/STAT3/VEGF signal transduction pathway against hepatocellular carcinoma." (PMID 37333486, 2023). "In hepatocellular carcinoma, blocking STAT3 activity using the STAT3 ODN-decoy led to the inhibition of proliferation and cell cycle progression of HepG2, PLC/PRF/5, and H7402 cells." (PMID 38067351, 2023). "Patient-derived hepatocellular carcinoma (HCC)-CAFs secrete IL-6 which induces PD-L1 expression on neutrophils via the STAT3 pathway." (PMID 37480115, 2023).
hepatocellular carcinoma (continued). "Beclin-1 is one of the key proteins of autophagy progress Research has shown that sorafenib and its derivative sc-59 induce hepatoma autophagy through the SHP-1/STAT3/MCL-1/Beclin-1 pathway." (PMID 37181755, 2023). "Thyroid hormone T3 inhibits IL-6 signaling in macrophages and hepatocellular carcinoma cells, suppresses STAT3 activation, and prevents the deleterious effects of excess hormone signaling during infection." (PMID 38022688, 2023). "Inducing the EMT process and angiogenesis, the IL-6/STAT3 signaling acts an important effect in many solid tumor progressions, such as hepatocellular carcinoma and colorectal cancer 38-42." (PMID 37781036, 2023). "Another investigation showed that the expanded TAM-inferred IL-6 has an intensifying impact on the inflammation responses, advancing the event and improvement of hepatocellular carcinoma as liver cancer employing STAT3 signaling." (PMID 37211559, 2023). "A study on hepatocellular carcinoma cells confirmed that STAT3 signaling is involved in hepatitis E virus replication." (PMID 37784164, 2023). "TAM-derived IL-6 induces tumorigenic and invasive effects and promotes breast, colorectal, and hepatocellular cancer or gastric tumor chemoresistance through the STAT3 signaling pathway." (PMID 36838713, 2023). "For example, UA reduced the expression of Stat3 and its downstream targets to inhibit the proliferation of prostate cancer and hepatocellular carcinoma." (PMID 37089712, 2023). "Such as, in hepatocellular carcinoma, STAT3-mediated lncRNA HOXD-AS1 acts as ceRNA to promote the metastasis of hepatocellular carcinoma." (PMID 36793374, 2023). "Oct4/Nanog co-expression is also a strong independent predictor of tumor recurrence and unfavorable outcome in hepatocellular carcinoma (HCC) by promoting EMT through activation of Stat3/Snail signaling." (PMID 37369946, 2023). "It was found that miR-515-5p inhibits hepatocellular carcinoma progression by inhibiting IL6/JAK/STAT3." (PMID 38025711, 2023). "Of note, it has been recently shown the involvement of a Cu-dependent amine oxidase in the activation of the IL6/JAK/STAT3 axis required for the progression of hepatocellular carcinoma." (PMID 36454513, 2023). "For example, human hepatocellular carcinoma-derived CAFs can secrete IL-6, which upregulates the activation of the STAT3 signaling pathway in DCs and creates a regulatory DC (rDC) phenotype that can’t prime and activate T lymphocytes." (PMID 37007004, 2023). "The activation of the STAT3 pathway in sorafenib-resistant cells has also been observed in previous studies of hepatocellular carcinoma, indicating that STAT3 inhibition enhances tumor cell sensitivity to sorafenib." (PMID 37887047, 2023). "Blockage of STAT3 by shRNAs has shown excellent results in suppressing the progression of HBV-related hepatocellular carcinoma (HCC)." (PMID 37784164, 2023). "In vitro analysis of IFNα-treated primary hepatocytes and human hepatoma-derived cells showed that hepcidin mRNA was upregulated, as was STAT-3." (PMID 36930080, 2023). "In conclusion, our study demonstrates that metformin promotes ferroptosis and sorafenib sensitivity in hepatocellular carcinoma cells via ATF4/STAT3." (PMID 37326750, 2023). "High expression of GUSBP11 in renal cancer is associated with a smaller tumor size and absence of metastasis, and SLC2A1-AS1 inhibits hepatocellular carcinoma progression and glycolysis through the STAT3/FOXM1/GLUT1 axis." (PMID 37020128, 2023). "It promotes IL6 expression, and IL-6 promotes STAT3 phosphorylation, which activates the IL-6/STAT3 pathway and thus enhances the proliferation of hepatocellular carcinoma cells." (PMID 37680619, 2023). "A phase I clinical study has investigated the therapeutic effect of OPB-111077, a novel STAT3 inhibitor, in patients with advanced hepatocellular carcinoma, which was proved to be well-tolerated." (PMID 36544761, 2022).
hepatocellular carcinoma (continued). "For example, TINCR can promote hepatocellular carcinoma proliferation and invasion via regulating STAT3 signaling." (PMID 35067169, 2022). "For instance, GYY4137 induces apoptosis in hepatocellular carcinoma cell lines by inhibiting STAT3 activators and downregulating B cell lymphoma 2 through STAT3." (PMID 35684331, 2022). "In hepatocellular carcinoma, STAT3 activated by LPS increases the production of VEGF by tumor cells, which promotes the proliferation and angiogenesis of HCC cells." (PMID 35563650, 2022). "For example, sulforaphane, a well-known isothiocyanate, has been reported to suppress STAT3 activation in a hepatocellular carcinoma cell line." (PMID 35877425, 2022). "In hepatoma cell lines and in situ hepatoma murine models, the receptor-mediated endocytosis of ConA is necessary for STAT-3 translocation to the nucleus and transducing its signals." (PMID 36289525, 2022). "Meanwhile, suppressed proliferation in hepatocellular carcinoma cells or the inhibition of glycolysis was achieved by the blocking of the JAK2/STAT3 pathway." (PMID 36431990, 2022). "Macrophages produce growth factors for cancer cells such as IL‐6, which is critical for hepatocellular carcinoma, via Stat3 activation." (PMID 35132816, 2022). "While targeting the STAT3 pathway, OC reduced cell proliferation and progression of melanoma and of human hepatocellular carcinoma." (PMID 36139836, 2022). "Upon culture in conditioned medium derived from hepatocellular carcinoma cells pre-treated with STAT3 decoy, NK cells showed a more activated phenotype with higher expression of IFNγ, granzyme and perforin." (PMID 35865518, 2022). "have evaluated CAF-regulated neutrophil function and the activation of hepatocellular carcinoma (HCC) via the IL-6/STAT3/PD-L1 signaling cascade." (PMID 35464435, 2022). "In regarding to the downstream of TMED3 in tumor, a previous study proposed that TMED3 promoted metastasis of hepatocellular carcinoma and served as a contributor in tumor progression via IL-11/STAT3 signaling pathway." (PMID 35854294, 2022). "In hepatocellular carcinoma cell lines, a STAT3 decoy resulted in upregulation of NKG2D ligands and increase of NK cell-mediated killing." (PMID 35865518, 2022). "Hyperuricemia response affects the expression of PDZK1; PDZK1 affects the proliferation, migration, and apoptosis through the STAT3/C-myc pathway in hepatocellular carcinoma." (PMID 36420358, 2022). "A recent study demonstrated that HAMP, as a tumor suppressor gene of hepatocellular carcinoma, downregulation contributes to proliferation, aggressiveness, and metastasis of hepatocellular carcinoma via the cyclin 4-dependent kinase-1/STAT3 pathway." (PMID 36585741, 2022). "Research indicated that the cross-talk between DDR1 and signal transducer and activator of transcription 3 (STAT3) promoted the progression of hepatocellular carcinoma (HCC) via epithelial–mesenchymal transition (EMT) and glutamine metabolism." (PMID 35935941, 2022). "The lncRNA SLC2A1-AS1 is able to regulate aerobic glycolysis and development of hepatocellular carcinoma by inhibiting the STAT3/FOXM1/GLUT1 signaling pathway." (PMID 35874626, 2022). "A Study showed that PD‐L1 reduces sorafenib resistance in hepatocellular carcinoma through STAT3/DNMT1 axis." (PMID 36372977, 2022). "For example, MUC1 was shown to promote radioresistance in hepatocellular carcinoma cells through activation of JAK2/STAT3 signaling." (PMID 35410995, 2022). "In vitro, TGR5 activation strongly inhibits hepatocellular carcinoma proliferation and migration by inhibiting STAT3 signaling and its DNA-binding activity." (PMID 36338742, 2022). "It has been demonstrated that HBX contributes to the activation of STAT3 to control the EMT of hepatoma cells." (PMID 35251017, 2022). "LncRNA SLC2A1-AS1 affects aerobic glycolysis and progression by inhibiting STAT3/FOXM1/GLUT1 signaling pathway in hepatocellular carcinoma." (PMID 35090515, 2022).
hepatocellular carcinoma (continued). "The aim of the present study was to clarify the molecular mechanism of CB-PIC in hepatocellular carcinoma cells targeting the Warburg effect via regulation of STAT3 and pyruvate signaling." (PMID 35742904, 2022). "This is consistent with previous reports that GA inhibits STAT3 phosphorylation in the treatment of colon cancer, psoriasis, and hepatocellular carcinoma." (PMID 35967372, 2022). "In a study on HCC, TAM-released IL-6 promoted the progression of hepatocellular carcinoma stem cells through STAT3 signaling." (PMID 35733919, 2022). "We focused on the precise effect of extract from leaves ofAzadirachta indica Juss, on inhibiting the IL-6/STAT3 signaling cascade on hepatocellular carcinoma byin vitro andin vivo study." (PMID 37829248, 2022). "STAT3 is known to regulate miR-146a expression in hepatocellular carcinoma cells and miR-155 in T-helper 17 cells." (PMID 34563711, 2022). "The silencing of CXCR7 also inhibits the migration and invasion of tumor endothelial cells from hepatocellular cancer by inhibiting STAT3." (PMID 35264069, 2022). "IL-37 overexpression by TAMs derived from patients with human hepatocellular carcinoma (HCC) inhibits M2 polarization via regulation of the IL-6/STAT3 pathway, to suppress tumor growth in vivo." (PMID 36551790, 2022). "Moreover, another study on hepatocellular carcinoma (HCC), where the increased expression of ERp57/PDIA3 was a marker of poor prognosis, revealed a specific role of ERp57/PDIA3 in association with phosphorylated (pY705) STAT3 on HCC progression." (PMID 35109791, 2022). "In support of this finding, hepatocellular carcinoma cells treated with STAT3 decoy secrete higher levels of IFNs and lower levels of immune suppressive TGF-β." (PMID 35865518, 2022). "The p-STAT3 has also been a key protein related to epithelial-mesenchymal transition (EMT) in hepatoma cells, and its elevated level indicated the tendency of EMT in inflammatory hepatocytes." (PMID 36324154, 2022). "Specifically, the IL-6/STAT3 signaling pathway was also confirmed to be inhibited in M1-type macrophages but activated in M2-type macrophages in hepatocellular carcinoma (HCC)." (PMID 35432300, 2022). "Overall, these studies agree with the fact that miRNA/EZH2 axis can affect proliferation, metastasis, and therapy response of hepatocellular carcinoma cells, and in this way, different molecular pathways such as Wnt, STAT3 and EMT are affected." (PMID 35236381, 2022). "Huang L found that RPN2 promotes metastasis of hepatocellular carcinoma cell and inhibits autophagy via STAT3 (signal transducer and activator of transcription-3) and NF-κB pathways." (PMID 33692975, 2021). "MEK/ERK/STAT3 pathway has been found to be involved in regulating the proliferation, invasion and migration of ovarian cancer cells and hepatocellular carcinoma cells." (PMID 34496800, 2021). "miR-149 inhibits the proliferation and migration of hepatocellular carcinoma cells and hepatocarcinogenesis by impeding the NF-κB and STAT3 signaling pathways." (PMID 34957298, 2021). "Previous studies reported that Icaritin inhibits the growth of liver cancer cells through promoting the apoptosis of hepatoma cells by activating the caspase pathway and inhibiting the IL-6/Jak2/Stat3 signaling pathway." (PMID 33794968, 2021). "STAT3 is a major oncogenic transcription factor that is constitutively activated in many types of human cancers, including hepatocellular carcinoma (HCC) and multiple myeloma (MM)." (PMID 34771643, 2021). "This compound is considered to be an inhibitor of the signal transducer and activator of transcription 3 (STAT3), an important constituent of hepatocellular carcinoma." (PMID 34961091, 2021). "For example, a responsive cytokine of the IL-6/STAT3 signalling pathway, IL-23 has been reported to promote the malignant properties of hepatoma cells." (PMID 34078370, 2021).